CORO1A (coronin 1A)
Diseases named in the same sentence as CORO1A in open-access papers (continued):
Sharing a sentence is not in itself a finding about the gene and the disease.
mastitis (1 paper, 2025). Inflammation of breast tissue during lactation or postpartum due to an obstructed duct or infection. "Nonetheless, the aberrant activation of the CORO1A observed in mammary gland tissues in this study provides meaningful insights into the immunoregulatory processes underlying clinical mastitis." (PMID 40563467, 2025). "In conclusion, CORO1A upregulation may activate immune and phagocytic responses, disrupting MGs’ immune homeostasis during Staphylococcus aureus-induced mastitis." (PMID 40563467, 2025). "Notably, CORO1A is involved in most of the BPs related to immune homeostasis, which highlights its critical involvement in the development of cow mastitis." (PMID 40563467, 2025). "The expression levels of CORO1A and TLR2 mRNA and proteins were positively correlated with the incidence of mastitis." (PMID 40563467, 2025). "Although CORO1A has not been widely studied in mastitis, and baseline expression data in healthy mammary glands are currently lacking, previous studies have linked it to immune signaling and phagocytosis." (PMID 40563467, 2025). "However, our results showed that the mRNA and protein expression of CORO1A and TLR2 was abnormally upregulated during mastitis." (PMID 40563467, 2025).
metastatic carcinoma (1 paper, 2025). A carcinoma which has spread from the original site of growth to another anatomic site. "Coronin 1A (CORO1A) has been up-regulated in metastatic carcinomas and proposed as a biomarker for metastasis." (PMID 40429863, 2025).
nephritis (1 paper, 2020). Inflammation of renal tissue. "Most importantly, experiments in humans showed that measurement of Coronin-1A in human sera using MRM-MS can segregate LN patients from SLE patients without nephritis with a high sensitivity (100%) and specificity (100%)." (PMID 32552896, 2020). "We showed for the first time that Coro1A is secreted in human serum and can distinguish LN patients from SLE patients without nephritis with high sensitivity and specificity." (PMID 32552896, 2020). "Coro1A showed a sensitivity of 100% and a specificity of 100% in classifying LN cases and SLE without nephritis cases, using 37.24 ng/ml as a cut-off." (PMID 32552896, 2020). "Most importantly, unsupervised consensus clustering between LN and SLE patients without nephritis showed clustering of LN patients and SLE into two distinct groups, based on their serum Coro1A concentration levels." (PMID 32552896, 2020).
non-small cell lung carcinoma (1 paper, 2023). A group of at least three distinct histological types of lung cancer, including non-small cell squamous cell carcinoma, adenocarcinoma, and large cell carcinoma. "CORO1A was associated with the TNM stage in non-small cell lung cancer." (PMID 37274231, 2023).
pancreatic cancer (1 paper, 2022). "Comparing the different responses of coro1a: GFP+ and mpx: GFP+ cells in in zebrafish xenografts, we hypothesize that macrophages might be the major population that quickly respond to the pancreatic cancer cells in the TME." (PMID 35742884, 2022).
pancreatic ductal adenocarcinoma (1 paper, 2023). An infiltrating adenocarcinoma that arises from the epithelial cells of the pancreas. "Analysis of large cohort data from The Cancer Genome Atlas revealed that expression of CORO1A, CORO1B, CORO1C, CORO2A, and CORO7 was significantly upregulated in pancreatic ductal adenocarcinoma (PDAC) tissues (p < 0.05)." (PMID 37239355, 2023).
renal fibrosis (1 paper, 2024). A final common manifestation of a wide variety of chronic kidney diseases characterized by glomerulosclerosis and tubulointerstitial fibrosis. "While in this study, drawing from transcriptome and single-cell sequencing data of patients with kidney fibrosis in public databases, we identified four core genes significantly associated with renal fibrosis, namely CD3G, CORO1A, FCGR2A, and GZMH." (PMID 38378674, 2024). "Logistic analysis, LASSO-based tenfold cross-validation, and gene topological analysis within Cytoscape identified four core genes (CD3G, CORO1A, FCGR2A, and GZMH) associated with renal fibrosis." (PMID 38378674, 2024). "Through logistic analysis, tenfold cross-validation with LASSO, and gene topological analysis in Cytoscape, we pinpointed four core genes significantly associated with renal fibrosis: CD3G, CORO1A, FCGR2A, and GZMH." (PMID 38378674, 2024).
rheumatoid arthritis (1 paper, 2014). A chronic, systemic autoimmune disorder characterized by inflammation in the synovial membranes and articular surfaces. "Proteins not previously reported to be associated with rheumatoid arthritis including, coronin-1A (CORO1A), fibrinogen like-2 (FGL2), and macrophage capping protein (CAPG) were found to be upregulated in rheumatoid arthritis." (PMID 24393543, 2014).
spina bifida aperta (1 paper, 2022). "The expression of coronin 1A and dynamin 2 was exosome-specific and associated with spina bifida aperta embryogenesis." (PMID 35915349, 2022).
viral myocarditis (1 paper, 2024). Myocarditis that is caused by an infection with a viral agent. "We observed a significant enrichment in terms associated with viral myocarditis (KEGG Pathway hsa05416) and leukocyte transendothelial migration (KEGG Pathway hsa04670), illustrated by the positive regulation of several genes from the cytoskeleton (actin, coronin 1A, RAC1...)." (PMID 39185406, 2024).
tumor (23 papers, 2008 to 2025). "Furthermore, the aberrant overexpression of CORO1A is linked to increased tumor malignancy, and preclinical evidence strongly supports CORO1A as a biomarker for cancer metastasis 6,11." (PMID 39629122, 2024). "Cell-skeleton-related genes like CORO1A influence their shape, movement, and phagocytic function, thereby altering their motility and functional state within the tumor microenvironment." (PMID 41394809, 2025). "AB also inhibited cell migration and ROS production, with CORO1A knockdown alleviating these tumor phenotypes, indicating that AB induces TNBC inhibition in a CORO1A-dependent manner." (PMID 39629122, 2024). "IHC staining showed that the decreased CORO1A protein expression and proliferation ability of tumor cells, and increased necrosis and apoptosis proportion of xenograft tumor tissues induced by AB were all weakened by MLN4924." (PMID 39629122, 2024). "IHC staining showed that AB induced an increased necrosis and apoptosis proportion of xenograft tumor tissues, a decreased proliferation ability of tumor cells, and reduced CORO1A protein expression." (PMID 39629122, 2024). "Coronin 1A (CORO1A), a 57 kDa protein, is a key member of this family and is closely associated with tumor migration 6,9." (PMID 39629122, 2024). "Consistently, the analysis of the GSE21422 database revealed that the CORO1A level in tumor samples was higher than that in normal tissues." (PMID 39629122, 2024). "In our research, PANC1 and BxPC3 recruited more coro1a: GFP+ innate immune cells to the TME compared to AsPC1 cells, and the co-localization of coro1a: GFP+ cells with the tumor cells was increased from 1 dpi to 4 dpi by three-fold for PANC1 and BxPC3." (PMID 35742884, 2022). "Compared to PANC1 and BxPC3 tumor, coro1a: GFP+ cells from AsPC1 xenografts expressed a low level of TNF-α and IL-12, and a higher level of IL-10." (PMID 35742884, 2022). "Studies have showed that HMGCR and CORO1A were involved in regulating T-cell homeostasis, which was important for the tumor microenvironment." (PMID 36313565, 2022). "At 4dpi, PANC1, BxPC3, and AsPC1 all recruited comparable neutrophils to the tumor, and to a much lesser degree compared to coro1a: GFP+ cells." (PMID 35742884, 2022). "In Coro1a−/− tumour‐bearing mice, the proportion of CD8+ T cells in the dLNs was significantly increased." (PMID 34623756, 2021). "Collectively, these data suggest that tumour development can be affected by the Coro1a‐mediated regulation of EV secretion." (PMID 34623756, 2021). "We found that in AB cells, Coro1A regulated cytoskeletal dynamics and interactions between mitochondria and cytoskeleton, thereby regulating the migration of these tumor cells." (PMID 32742496, 2020). "However, the precise relationship between CORO1A and tumor biology will be revealed in further studies." (PMID 38424522, 2024). "We observed a similar tendency in the MC38 Coro1a−/− tumor-bearing mice." (PMID 36220994, 2022). "We then investigated tumour growth when Coro1a was used as a target to regulate EV secretion." (PMID 34623756, 2021). "In addition to its role as a target in tumours, Coro1a probably holds high potential as a target in other diseases in which EVs are involved." (PMID 34623756, 2021). "Furthermore, a decrease in neddylated Coro1a enhances the production of tumour EVs, thereby promoting tumour progression, indicating that neddylated Coro1a is an ideal target for the regulation of EV biogenesis." (PMID 34623756, 2021). "Furthermore, we confirmed that Coro1a is an effective target for the regulation of EVs when exemplified in the mouse tumour model." (PMID 34623756, 2021). "In addition, we found that the knockout of Coro1a greatly inhibited tumour progression and enhanced antitumour immunity by reducing EV secretion." (PMID 34623756, 2021).
tumor (continued). "Supplementation with the same quantity of EVs from MC38 cells (MC38‐EVs) and from MC38‐Coro1a−/‐ cells (MC38‐Coro1a−/−‐EVs) equally rescued the growth inferiority of Coro1a−/− tumour and shortened the survival, suggesting that Coro1a knockout did not alter EV function." (PMID 34623756, 2021). "These analyses revealed significantly higher rates of Coro1A positivity in AB samples relative to controls (not shown), with this high expression being closely linked to tumor recurrence rate." (PMID 32742496, 2020). "Interestingly, the authors found that CORO1A was not overexpressed in renal cancer cells, but instead in the infiltrating lymphocytes localized in the tumor microenvironment, whereas ADFP overexpression was associated with tumor cells." (PMID 32742246, 2020). "Six genes—ARHGEF19, CORO1A, ACOT7, ZC3H18, SLC5A5, and ZFAS1—showed statistically significant differential expression between tumor and normal tissues (P < 0.05)." (PMID 40070828, 2025). "We also studied the effects of HCLS1, CORO1A and CCRL2 on tumor metastasis-related indicators at the cellular level through in vitro experiments." (PMID 37274231, 2023). "Similar to the results from the MC38 Rab27a−/− tumor-bearing mice, αPD-L1 notably inhibited MC38 Coro1a−/− but not MC38 tumor growth at the same dose." (PMID 36220994, 2022). "In addition to CORO1A, THBS1, PTP4A1, IL6, and CXCL16, the other nine genes were also upregulated in tumor tissues in TCGA." (PMID 32883954, 2020). "Thus, coro1a: GFP+ immune cells are likely active and probably phagocytosing the tumor cells." (PMID 35742884, 2022). "Thus, CORO1A, DPP4 and ANXA5 might play the significant roles in some common biological process of tumor." (PMID 33407865, 2021).
infection (12 papers, 2010 to 2025). The state of being infected such as from the introduction of a foreign agent such as serum, vaccine, antigenic substance or organism. "For example, the Staphylococcus aureus LMW-PTP, PtpA, is secreted during macrophage infection and interacts with the cytoskeletal associated protein, coronin-1A." (PMID 34015051, 2021). "Overall, between 50% and 75% of C. albicans-infected coro1a:GFP-rac2D57N zebrafish showed hyphal growth of varying degrees throughout the infection." (PMID 40197062, 2025). "Additionally, more coro1a-driven macrophage and neutrophil cells in Cu2+-stressed embryos were recruited to the infection and wounded domain from 0 to 6 hpi." (PMID 31787979, 2019). "GSEA at 24 h indicated that genes involved in infection, TLR, chemokine and cytokine signaling are enriched as before, but genes involved in phagocytosis are also enriched, including Vav1, Sirpa, Cdc42se1, Cdc42ep2, Fcgr2b/3, and Coro1a." (PMID 25888408, 2015). "Moreover, a potential interaction between CORO1A and the TLR2 signaling pathway may enhance the bactericidal activity of macrophages during phagocytosis, thereby facilitating pathogen clearance at infection sites." (PMID 40563467, 2025). "However, it is important to note that coro1a:GFP-rac2D57N fish also showed an innate sensitivity to burn wound injury, and excessive tissue necrosis and death were observed even in the absence of infection." (PMID 40197062, 2025).
cancer (10 papers, 2013 to 2025). A tumor composed of atypical neoplastic, often pleomorphic cells that invade other tissues. "Compared with normal breast tissues, PIGR, GPLD1, PLA2G5 and CORO1A were down-regulated in cancer tissues, while EIF4EBP1 and LPCAT1 were significantly up-regulated." (PMID 41450825, 2025). "Coro1A, on the other hand, has been shown to promote cell death in certain cancer cells by activating apoptotic signalling." (PMID 38877505, 2024). "For example, the LAPTM5-a7 transcript (transcribed from the LAPTM5 gene) and CORO1A-u2 transcript (an unannotated transcript from the CORO1A gene) are exclusively expressed in cancer cell lines derived from haematopoietic and lymphoid lineages." (PMID 36357395, 2022). "By analyzing the shared immune features of primary cancers and lymphatic metastases, we unraveled the prognostic value and joint utility of two DEGs, CORO1A and S100A8." (PMID 34337026, 2021). "Filamin A (FLNA), plastin-2 (LCP1), coronin-1A (CORO1A), and formin-like-1 (FMNL1) also affect cytoskeletal dynamics by modulating actin filaments which eventually prompt cancer mobility and invasion." (PMID 32326232, 2020).
bacterial infection (2 papers, 2014 to 2019). "Cell RNA-Seq analysis revealed that Jak-STAT signaling, which has important function in immune responses to bacterial infection, was enriched for DEGs in copper-stressed coro1a-, mpx-, and lyz-positive cells." (PMID 31787979, 2019). "Coronin 1A (Coro1A) plays important roles in host against bacterial infection, yet little is known about porcine Coro1A." (PMID 25093672, 2014).
genetic disease (1 paper, 2023). "Among protein-coding genes located between BP4 and 5, five genes, including TAOK2 (a pLI score of 1.00), CORO1A (0.97), MAZ (0.93), PAGR1 (0.74), and PRRT2 (0.59), have a pLI value of 0.5 or more and are associated with symptoms related to 16p11.2 deficits and are implicated in genetic disease." (PMID 38203422, 2023).
infectious disease (1 paper, 2014). A disorder directly resulting from the presence and activity of a microbial, viral, or parasitic agent in humans. "However, the molecular characterization of porcine Coro1A and its potential roles in porcine infectious diseases have not been studied." (PMID 25093672, 2014).
renal disease (1 paper, 2020). "Quantification of Coro1A in sera of larger, well-annotated patient cohorts will provide further evidence for its role in renal disease, as well as its value as a screening LN biomarker." (PMID 32552896, 2020). "These preliminary findings suggest that serum Coronin-1A may serve as a promising non-invasive biomarker for LN and, upon validation in larger cohorts, may be employed in the future as a screening test for renal disease in SLE patients." (PMID 32552896, 2020).
CORO1A also shares sentences with these, for which no sentence is quoted: Primary immunodeficiencies (3 papers); Anxiety (2); asthma (2); combined immunodeficiency (2); Intellectual disability (2); triple-negative breast carcinoma (2); acute myeloid leukaemia (1); ameloblastoma (1); amyotrophic lateral sclerosis (1); ataxia telangiectasia (1); B-cell lymphopenia (1); bladder tumor (1); breast tumors (1); chronic bronchitis (1); coagulopathies (1); Cognitive impairment (1); colitis (1); colorectal adenoma (1); colorectal cancer (1); COVID-19 (1); developmental delay (1); gastric cancer (1); glycogen storage disease (1); Granuloma (1); Hepatitis (1); Immunodeficiency 8 (1); inflammatory bowel disease (1); latent infection (1); Legionnaires' disease (1); leishmaniasis (1).
A further 18 diseases each share a sentence with CORO1A in 1 paper.